SFI1 (SFI1 centrin binding protein)
Description:
Plays a role in the dynamic structure of centrosome-associated contractile fibers via its interaction with CETN2.
Synonyms: KIAA0542; PISD; PPP1R139; hSfi1p
Tractability: PROTAC: ubiquitination databases record sites on it.
Gene: Protein-coding gene on chromosome 22 (31,488,688 to 31,618,588, forward strand). Ensembl gene ENSG00000198089.
Subcellular location: Cytoplasm, cytoskeleton, microtubule organizing center, centrosome, centriole
Pathways (Reactome):
Cell Cycle: AURKA Activation by TPX2; Loss of Nlp from mitotic centrosomes; Loss of proteins required for interphase microtubule organization from the centrosome; Recruitment of NuMA to mitotic centrosomes; Recruitment of mitotic centrosome proteins and complexes; Regulation of PLK1 Activity at G2/M Transition
Organelle biogenesis and maintenance: Anchoring of the basal body to the plasma membrane
Gene Ontology:
Molecular function: phosphatase binding; protein binding
Cellular component: centriole; cytosol
Genetic constraint (gnomAD): Loss-of-function variants: 173 observed, 183.04 expected, observed/expected ratio (o/e) 0.95, 90% interval 0.83 to 1.07. The upper end of that interval is the gene's LOEUF score, 1.07, which puts it in group 4 of 6, group 1 being the genes least tolerant of losing a copy. Missense variants: 1,561 observed, 1,496.6 expected, observed/expected ratio (o/e) 1.04, 90% interval 1 to 1.09. Synonymous variants: 603 observed, 567.91 expected, observed/expected ratio (o/e) 1.06, 90% interval 0.99 to 1.14.
Homologues: Orthologues: chimpanzee SFI1 (98% identical), macaque SFI1 (90% identical), dog SFI1 (73% identical), guinea pig SFI1 (66% identical), rabbit SFI1 (66% identical), mouse Sfi1 (63% identical), rat Sfi1 (63% identical), pig SFI1 (55% identical), tropical clawed frog sfi1 (36% identical), zebrafish sfi1 (26% identical), Drosophila melanogaster CG17258 (7% identical). Paralogues in human: CCDC191 (9% identical).
Diseases named in the same sentence as SFI1 in open-access papers:
SFI1 is named in the same sentence as 11 diseases in open-access papers, as found by Europe PMC text mining. Sharing a sentence is not in itself a finding about the gene and the disease. The quoted sentences say what the papers report.
autism (1 paper, 2014). Persistent deficits in social interaction and communication and interaction as well as a markedly restricted repertoire of activity and interest as well as repetitive patterns of behavior. "There is some evidence for an association between a linkage block at 2q31.1 containing METAP1D and autism, whilst copy number variants encompassing SFI1 have previously been identified in autism and related developmental disorders." (PMID 24602487, 2014).
carotid artery dissection (1 paper, 2024). Spontaneous or traumatic separation of the layers of the carotid artery wall. "SFI1, a centriolar protein, regulates centriole replication, with polymorphisms linked to myocardial infarction, coronary artery disease, and carotid artery dissection susceptibility (HPO)." (PMID 39457085, 2024).
glioma (1 paper, 2014). A benign or malignant brain and spinal cord tumor that arises from glial cells (astrocytes, oligodendrocytes, ependymal cells). "Cloning insertions from these SB-induced gliomas identified Sfi1, Csf1, Mkln1, Vps13a and Fli1 as common insertion sites (CISs) which are chromosomal regions that are insertionally mutated in more tumors than would be expected by random chance and represent candidate glioma genes." (PMID 25423036, 2014).
schizophrenia (1 paper, 2018). A major psychotic disorder characterized by abnormalities in the perception or expression of reality. "To test whether the expression of SFI1 mRNA is associated with the pathophysiology of schizophrenia, we measured SFI1 mRNA expression in hair follicle cells from schizophrenic and healthy control subjects 33,34." (PMID 29391571, 2018). "The SFI1 mRNA expression in the hair follicle cells of patients with schizophrenia was significantly lower than that of healthy controls." (PMID 29391571, 2018). "Western blot analysis showed that SFI1 expression in the parietal cortex of patients with schizophrenia was significantly higher than that of controls." (PMID 29391571, 2018). "Interestingly, we found altered expression of SFI1 in the postmortem brains and SFI1 mRNA in hair follicle cells from patients with schizophrenia compared with controls." (PMID 29391571, 2018). "Finally, we found altered expressions of SFI1 in the parietal cortex and SFI1 mRNA in hair follicle cells of patients with schizophrenia, suggesting that abnormal expression of SFI1 plays a role in the pathogenesis of schizophrenia." (PMID 29391571, 2018). "In this study, SFI1 mRNA expression in the hair follicle cells of patients with schizophrenia was lower than that of healthy controls although SFI1 protein expression in the parietal cortex from patients with schizophrenia was higher than that of controls." (PMID 29391571, 2018).
SFI1 also shares sentences with these, for which no sentence is quoted: autism spectrum disorder (1 paper); cancer (1); coronary artery disease (1); gastric cancer (1); myocardial infarction (1); neurodevelopmental disorder (1); tumor (1).